RHOC (ras homolog family member C)
Diseases named in the same sentence as RHOC in open-access papers (continued):
Sharing a sentence is not in itself a finding about the gene and the disease.
tumor (continued). "RhoC also contributes to tumor development, especially to invasion and metastasis of cancer cells." (PMID 19374769, 2009). "Specifically, the levels of RhoC expression were significantly correlated with the extents of local intestinal invasion although not with the histopathological degrees of cancers, strongly supporting its function in tumor invasion and metastasis." (PMID 19374769, 2009). "Furthermore, Faried A. and colleagues identified that RhoA promoted tumour growth more than RhoC, while RhoC induced distant metastasis in comparison to RhoA." (PMID 19374769, 2009). "Recently, emerging data suggest that RhoC gene may have a potential role in carcinogenesis and metastasis of tumour cells." (PMID 15150600, 2004). "Only for rhoB and rhoC, about 30% of the tumours exhibited increase in mRNA levels." (PMID 12237774, 2002). "Metastatic lesions overexpressed the rhoC gene compared with primary tumours (P < 0.05)." (PMID 9459160, 1998). "On another hand, the presence of RhoC-specific T cells before vaccination or in the placebo control group strongly suggests that in vivo T cell priming was taking place in some patients; hence, that RhoC is a tumor antigen that can spontaneously give rise to T cell responses." (PMID 40333248, 2025). "Our results indicated that the overexpression of RhoC was closely related to tumor metastasis of OSCC, while knockdown of RhoC restrained the invasion and metastasis capability of OSCC cells in vivo and in vitro, and these effects may be related to the regulation of HMGA2 expression." (PMID 33519932, 2021). "Thus, the findings indicate that the tumor-promoting effects of ABHD11-AS1 may be brought about via its effects on RhoC." (PMID 28818073, 2017). "Finally, tumor invasive factors RhoC, uPAR, MMP-2 and MMP-9 were also measured." (PMID 25236186, 2014). "Research data have shown that RhoC had an important role in cell migration and metastasis, but there were some contradictions about whether RhoC regulate the process of transformation and proliferation in tumor cells." (PMID 23145020, 2012). "Several studies have implicated RhoC as the predominant Rho GTPase in PC tumors and its expression is associated with metastasis and decreased survival (6 month versus 12 month for patients whose tumor expressed low or no RhoC)." (PMID 15969750, 2005). "Owing to its role in cytoskeletal reorganisation, in focal adhesion contacts and in tumour invasion, RhoC was chosen from the pool of 668 differentially expressed genes for further analysis of the possibility that increased RhoC expression might correlate with HCC metastasis." (PMID 15150600, 2004). "Several studies have shown that RHOA and RHOC positively contribute to tumor promotion, but the distinct role of RHOB as a tumor suppressor or an oncogene in cancer remains elusive." (PMID 34771549, 2021). "Increasing studies showed that both the Rho family and MMP family, including Rac1/2/3, CDC42, RhoA, RhoC, MMP2, and MMP9, are highly expressed in a variety of tumor tissues and are directly correlated with tumor migration and invasion." (PMID 33377649, 2020). "RhoC GTPase, an important regulator of cytoskeletal reorganization during cellular motility, is overexpressed in IBC tumor samples." (PMID 32883032, 2020). "Irrespective of the lack of exact mechanism of activation of nuclear RhoC, it is important to note that a subset of tumor cells, in the clinical samples, exhibit strong co-expression of ROCK2 and RhoC." (PMID 31488179, 2019). "RHOB has therefore been suggested to have a tumor suppressor role, while RHOA and RHOC are considered oncogenes." (PMID 31888022, 2019). "Previous studies have revealed that microRNA-10b promotes the metastasis of a variety of tumor cells by regulating Bim, TFAP2C, P16, P21, E-cadherin, CD138, RHOC, RhoC, uPAR, MMP-2, MMP-9, HOXD10, etc 23-29." (PMID 31592231, 2019). "We also report that both RhoC and ROCK2 are localized in the nuclear compartment in a subset of tumor cells." (PMID 31488179, 2019).
tumor (continued). "Interestingly, higher Pin1 and RhoC expression were significantly associated with smaller tumor, and high RhoA also demonstrated such trend, which might be due to dissemination of HCC cells from the primary tumor." (PMID 31324164, 2019). "RhoC and its downstream effector ROCK2 have been independently shown to regulate tumor progression in several tumor types." (PMID 31488179, 2019). "We therefore reverse engineered a static ARACNE mutual information network representing the neighbourhood of RND3, RHOC, RHOBTB1 and RHOBTB2 during the tumour implantation time course." (PMID 26132659, 2015). "The levels of the tumor initiators HER2 and KRAS and metastasis genes VEGF, CXCL-4, CCL5, NEDD9 and RHoC were reduced in MCF-7 cells with UBE2C knockdown and increased with UBE2C overexpression." (PMID 24699941, 2014). "Extra copies and overexpression of RHOC also occur, although a role for RhoC overexpression in driving tumor formation has not been assessed in vivo." (PMID 38807216, 2024). "RhoC, a member of the Rho-GTP family, is a key mediator of tumor cell migration and invasion." (PMID 33828938, 2021). "PCACP significantly inhibited HCC cell proliferation and tumor growth by targeting mTOR (mechanistic target of rapamycin), PAK4 (p21-Activated kinase 4), RHOC (Rho-related GTP-binding protein) and epithelial mesenchymal transition (EMT) pathways both in vitro and in vivo." (PMID 34072348, 2021). "We speculated that the RhoC/ROCK1 pathway activated by TEM8 could activate SMAD5, which was involved in the stemness of tumor cells and tumor angiogenesis." (PMID 34285210, 2021). "To date, the molecular mechanisms involved in RhoC promotion of tumor progression have not been fully understood." (PMID 33519932, 2021). "Proto-oncogenes are those genes that are involved in cell growth and proliferation, with potential examples including the ATM, FGFR2, FN1, IGF1, MAP3K, MMP7, and RHOC genes, while the CASP8 and LSP1 genes have been reported to possess tumor-suppressive properties in certain types of cancer." (PMID 33112566, 2020). "Despite a series of convincing reports on RhoC’s role in various tumor phenotypes, it has not been developed further as a prognostic marker or therapeutic target." (PMID 31340863, 2019). "It is important to note that RhoC, which is predominantly a cytosolic protein is observed in nuclear compartments of some of the tumor cells, an observation that has not been reported earlier." (PMID 31488179, 2019). "Additionally, immunohistochemical analysis of clinical specimens revealed that RhoC and VEGF were expressed in the same areas of tumor sections." (PMID 31340863, 2019). "We have shown that the inhibition of RhoC and ROCK2 sensitizes tumor cells to irradiation." (PMID 31488179, 2019). "It has been reported that macrophages enhance the migration of IBC cells through RhoC GTP signaling, and macrophages isolated from IBC patient samples secrete chemotactic cytokines that may increase IBC tumor cell dissemination and metastasis." (PMID 31532791, 2019). "When RhoC was knocked down (RhoC-KD) in ALDH+ cells, tumor initiation was severely impaired (i.e., no induction in the RhoC-KD group vs. 5/9 tumors formed in non-silencing control when 50 CSCs are injected in each group)." (PMID 31681564, 2019). "Although Rho GTPases RhoA, RhoB, and RhoC share more than 85% amino acid sequence identity, they play very distinct roles in tumor progression." (PMID 29385717, 2018). "Indeed, there is a significant increase in RhoC, Cdc42 and MYL9 expression levels in metastasis versus primary tumours, indicating that drivers of actomyosin contractility are selected during HCC metastatic dissemination." (PMID 27941881, 2017). "Previous studies showed that RhoC does not have any effect on cell proliferation in vitro or on tumour growth in mice but affects metastasis." (PMID 25677806, 2015).
tumor (continued). "We confirmed these results via Western blotting analysis of tumor cells expressing AFAP1-AS1 siRNA, and found that RhoA, Rac2, Rab10, Rab11a, Rhogdi and Pfn1 were significantly upregulated, but RhoC, Rab11b and Lasp1 were significantly downregulated in NPC cell lines." (PMID 26246469, 2015). "DLC1 (Deleted in Liver Cancer 1) gene encodes a RhoGTPase-activating protein (RhoGAP), which exerts most of its tumor suppressor functions through suppression of small Rho GTPases proteins RhoA, RhoB, RhoC and to some degree Cdc42, but not Rac." (PMID 24683532, 2014). "Protein expression studies indicated that in O-DDHSL treated cells no drastic changes were observed in case of IQGAP-1or RhoC in tumor cells except for HPDE cells." (PMID 25188245, 2014). "A study by Ikoma and colleagues showed that RhoC did not affect tumor growth but enhances the metastatic nature of lung cancer by stimulating cell motility." (PMID 23145020, 2012). "Surprisingly, RhoC often promoted spontaneous metastasis independent from primary tumor formation even within the non-BCSC population, suggesting that RhoC can act independent of BCSC status." (PMID 22911725, 2012). "Although tumour grade and stage were related to RhoC and ROCK-1 in ccRCC, they were not related to RhoB." (PMID 21119662, 2011). "Unlike RhoA and RhoC, the level of active-RhoB protein, which is a tumor suppressor gene, was up-regulated in both BxPC-3 and PanC-1 cells by BITC treatment." (PMID 22016776, 2011). "Correlation of RhoC with Notch1 and pAkt was assessed on serial sections of SCC tissues and all the molecules were found to be expressed in the same areas of the various tumour sections." (PMID 19953094, 2010). "Comparison of the BxPC-3 (derived from a primary tumor) and HPAF-II (derived from a metastasis) demonstrates a reciprocal relationship between cav-1 expression and p42/p44 Erk activation with PC cell migration, invasion, RhoC GTPase and p38 MAPK activation." (PMID 15969750, 2005). "Furthermore, increased expression of RhoC in HCC seemed to correlate positively with poor cell differentiation and with tumour vein invasion." (PMID 15150600, 2004). "We therefore argue that RhoC has general importance in tumour invasiveness and in the nonmetatstatic/metastatic switch, but not in the specific metastatic homing to the lungs." (PMID 12865923, 2003). "The expression levels of the rhoC gene were significantly higher in tumours than in non-malignant portions (P < 0.001)." (PMID 9459160, 1998). "Carcinoma tissues with perineural invasion and lymph node metastasis exhibited significantly higher expressions of the rhoC gene than tumours without these manifestations (P < 0.001 and P < 0.05 respectively)." (PMID 9459160, 1998). "Whether increased levels of wildtype RHOC promote tumor formation and/or progression in this context has never been determined." (PMID 38807216, 2024). "The lack of RhoC could inhibit the metastasis of tumor cells by regulating the interaction between tumor cells and endothelial cells." (PMID 36247874, 2022). "In addition, RhoC is also a key mediator in the proliferation and metastasis of tumor cells, and AKT could regulate RhoC expression." (PMID 36247874, 2022). "Overall, our study suggests that knockdown of RhoC expression is able to suppress the malignant biological behavior of OSCC, specifically the malignant properties of cell invasion, migration, tumor growth, and lymph node metastasis, and these might be achieved by regulating HMGA2 expression." (PMID 33519932, 2021). "As an important member of the Rho GTPase family member, RhoC plays a significant role in the invasion and metastasis of malignant tumors by influencing epithelial-mesenchymal transition (EMT), extracellular matrix degradation, cell migration, and tumor angiogenesis." (PMID 33519932, 2021). "Contrary to the role of RhoC in tumor metastasis, its role in tumor growth is not univocal." (PMID 29854771, 2018).
tumor (continued). "Therefore, in our study, the small GTPase RhoC was not overexpressed in the pulmonary metastases compared to the primary tumour of both cell lines." (PMID 12865923, 2003). "We could not detect any consistent difference in the expression of RhoC in pulmonary metastases compared to the primary tumour." (PMID 12865923, 2003). "The inverse relationship between RhoC expression and ALDH activity persisted in vivo; ALDH (+) SUM149 scrambled tumors maintained RhoC expression during tumor growth, whereas ALDH (−) SUM149 scrambled tumors did not regain RhoC expression." (PMID 22911725, 2012). "Here we discover that RhoC GTPase can promote BCSC metastasis and can initiate metastasis independent of primary tumor formation." (PMID 22911725, 2012). "A possibly important oncogene product in that context is RhoC GTPase, which was found to be overexpressed in 90% of archival IBC tumour samples, but not in stage-matched non-IBC tumours." (PMID 12618881, 2003). "Using an orthotopic xenograft model of spontaneous metastasis we discover that RhoC is both necessary and sufficient to promote SUM149 and MCF-10A BCSC metastasis–often independent from primary tumor formation–and can even induce metastasis of non-BCSCs within these cell lines." (PMID 22911725, 2012).
cancer (122 papers, 1998 to 2026). A tumor composed of atypical neoplastic, often pleomorphic cells that invade other tissues. "RhoC, which links membrane receptors with focal adhesions and actin/myosin networks and is associated with cancer cell stemness, migration, and angiogenesis, was downregulated, and many other proteins that were associated with cell cycling were also modulated." (PMID 41226720, 2025). "Rho GTPases including RhoA and RhoC, are a class of highly conserved small molecule proteins that regulate various physiological processes and are also implicated in cancer progression and metastasis." (PMID 31488179, 2019). "RhoC is a member of the Rho GTPase family that is implicated in cancer progression by stimulating cancer cell invasiveness." (PMID 25677806, 2015). "RhoC has been implicated in the enhancement of cancer cell migration and invasion, with actions which are distinct from RhoA (84% homology), and are possibly attributed to the divergent C-terminus domain." (PMID 24312560, 2013). "Increased expression of RhoC has been implicated in the metastatic process in pathologically distinct human cancers." (PMID 24312560, 2013). "Considering that both RhoC and IQGAP1 have role in regulating proliferation of cancer cells and their expressions were highly correlated, we further explored the functional association between RhoC and IQGAP1." (PMID 23145020, 2012). "RhoA has been implicated in virtually all stages of cancer progression and metastasis, whereas RhoC is restricted to metastasis." (PMID 22016776, 2011). "Our current study posits that functional RhoC contributes to increased IFN signaling in cancer cells, which would conflict with the logical conclusion from previous studies that RhoC is positively associated with M2 macrophages and M2 macrophages are negatively associated with IFN-α." (PMID 34513691, 2021). "Analysis of the COSMIC database suggests that mutations of RhoC in cancer are very rare." (PMID 31340863, 2019). "C12-HSL treatment induced cytoskeletal associated protein expression of vinculin and RhoC, which may have implications in cancer cell motility, adhesion, and metastasis." (PMID 29854771, 2018). "The involvement of miR-106b-mediated RhoC downregulation in EOC aggression may give extended insights into molecular mechanisms underlying cancer aggression." (PMID 25933027, 2015). "RhoC was one of the first genes reported to stimulate cancer cell metastasis in mice, and subsequent studies have linked its expression to metastasis in a wide range of human cancers." (PMID 25677806, 2015). "The involvement of miR-106b-mediated RhoC downregulation in EOC aggression may provide wider insight into the molecular mechanisms underlying cancer aggression." (PMID 25933027, 2015). "The involvement of miR-93-5P–mediated RhoC downregulation in inhibiting EOC aggressiveness may provide extended insight into the molecular mechanisms underlying cancer aggressiveness." (PMID 25649143, 2015). "The involvement of miR-93-5P–mediated RhoC downregulation in inhibiting EOC aggressiveness may yield further insight into the molecular mechanisms underlying cancer aggressiveness." (PMID 25649143, 2015). "Although RhoC has been implicated in cancer cell migration, the relevant underlying molecular mechanisms remain unknown." (PMID 24312560, 2013). "RhoA and RhoC proteins have implicated them as important factors in promoting the uncontrolled proliferation and invasive and metastatic properties of cancer cells, however, it is poorly understood how they are activated in cancer cells." (PMID 20828398, 2010). "The abnormally high expression of RhoC has been associated with the development of malignant tumors, such as head and neck cancers, ovarian cancer, and GC, and could promote the proliferation, invasion, and migration of cancer cells." (PMID 33082325, 2020).